GPR68 (G protein-coupled receptor 68)
Diseases named in the same sentence as GPR68 in open-access papers (continued):
Sharing a sentence is not in itself a finding about the gene and the disease.
triple-negative breast carcinoma (2 papers, 2022). An invasive breast carcinoma which is negative for expression of estrogen receptor (ER), progesterone receptor (PR), and human epidermal growth factor receptor 2 (HER2). "Also, in-silico and validation data revealed that the triple-negative breast cancer cell line MDA-MB-231 showed the highest expression of GPR68." (PMID 35311103, 2022).
acute myeloid leukemia (1 paper, 2021). Acute myeloid leukemia (AML) is a group of neoplasms arising from precursor cells committed to the myeloid cell-line differentiation. "Of note, we have identified targets of transcription repressor IKZF1 in MDS cells and acute myeloid leukemia (AML) cells, including G protein-coupled receptor 68 (GPR68) and regulator of calcineurin 1 (RCAN1)." (PMID 34680233, 2021). "We have found that lenalidomide-mediated degradation of IKZF1 leads to activation of the G protein-coupled receptor 68 (GPR68)/calcium/calpain pro-apoptotic pathway and inhibition of the regulator of calcineurin 1 (RCAN1)/calcineurin pro-survival pathway in MDS and acute myeloid leukemia (AML)." (PMID 34680233, 2021). "We have identified signaling molecules downstream of IKZF1, G protein-coupled receptor 68 (GPR68) and regulator of calcineurin 1 (RCAN1) in myeloid malignancies, including MDS and acute myeloid leukemia (AML) with or without del(5q)." (PMID 34680233, 2021).
age (1 paper, 2025). A temporal measurement of the time period elapsed since an identifiable point in the life cycle of an organism. "Researchers using hematopoietic cell-specific GPR68 conditional knockout mice have shown that targeting GPR68 enhances the function of aging hematopoietic stem cells, providing a novel therapeutic strategy for age-related hematopoietic decline." (PMID 41190345, 2025).
aneurysm (1 paper, 2022). Bulging or ballooning in an area of an artery secondary to arterial wall weakening. "Another major finding of this study is that elevated expression of Gpr68 in macrophages is responsible for the exacerbated aneurysms formation." (PMID 36400753, 2022).
aortic aneurysm (1 paper, 2022). A ruptured aneurysm located in the wall of the proximal portion of the descending aorta proceeding from the arch of the aorta. "The findings reveal that Tsc2 deficiency in macrophages contributes to aortic aneurysm formation, at least in part, by upregulating Gpr68 expression, which subsequently drives proinflammatory processes and matrix metallopeptidase activation." (PMID 36400753, 2022). "Gpr68 inhibition largely abrogated the progression of aortic aneurysms caused by Tsc2 deficiency in macrophages." (PMID 36400753, 2022). "Therefore, small molecule agents could be designed to block macrophage Gpr68 signaling to prevent aortic aneurysm development especially in patient with Tsc2 mutation." (PMID 36400753, 2022). "Targeting macrophage Gpr68 may represent a novel potential therapeutic approach to limit aortic aneurysm expansion." (PMID 36400753, 2022). "In summary, our data demonstrate that Tsc2 deletion triggers a proinflammatory phenotype in macrophages through the Gpr68/CREB pathway, thereby aggravating aortic remodeling and aortic aneurysm formation." (PMID 36400753, 2022).
bacterial meningitis (1 paper, 2024). Inflammation of the membranes surrounding the brain and spinal cord due to a bacterial infection. "The diagnostic value of GPR68, KIF5C OR52K2, and CCR5 were assessed in bacterial meningitis." (PMID 38347610, 2024). "In bacterial meningitis patients, 8 co-expression relationships were constructed between 8 mRNAs (ACBD7, OR52K2, GPR68, SHISA4, KIF5C, OR52P2P, OR51R1P, and CCR5) and 1 lncRNA." (PMID 38347610, 2024). "GPR68 and KIF5C, identified in bacterial meningitis co-expression analysis, had an area under the curve (AUC) of 1.00, while the AUC of OR52K2 and CCR5 is 0.883 and 0.698, respectively." (PMID 38347610, 2024). "Moreover, KIF5C, GPR68, and OR52K2, with higher AUC, may be potential diagnosis makers in bacterial meningitis." (PMID 38347610, 2024).
brain injury (1 paper, 2017). Acute and chronic (see also brain INJURIES, CHRONIC) injuries to the brain, including the cerebral hemispheres, CEREBELLUM, and brain STEM. "Other experiments have provided evidence that CHI3L1, GPR68 and IL1A are involved in the response to traumatic brain injury." (PMID 28097054, 2017).
breast tumor (1 paper, 2022). "First, we examined the expression of different acid sensors in human breast tumor specimens compared with normal mammary tissue and identified OGR1 (GPR68) and TDAG8 (GPR65) as being highly expressed in different subtypes of invasive breast carcinomas." (PMID 35545051, 2022).
cardiac hypertrophy (1 paper, 2025). "Ang II-treated male WT and Gpr68−/− mice had increased cardiac hypertrophy (shown as left ventricular posterior wall and heart-to-tibia length) compared with sham-treated mice." (PMID 40560060, 2025).
colorectal tumor (1 paper, 2023). "Overall, they concluded that GPR68 promotes colorectal tumor initiation in mice." (PMID 36902589, 2023).
dysplasia (1 paper, 2023). A usually neoplastic transformation of the cell, associated with altered architectural tissue patterns. "The significantly increased prevalence of severe dysplasia or SCC in tongues of GPR68−/− mice suggests a potential role for this gene in suppressing the initiation or progression of OED." (PMID 36611126, 2023). "We found that treatment with 4NQO resulted in similar numbers of tongue lesions between wild-type (GPR68+/+) and GPR68−/− mice; however, GPR68−/− mice were more likely to develop severe dysplasia and SCC." (PMID 36611126, 2023).
gastric cancer (1 paper, 2019). A primary or metastatic malignant neoplasm involving the stomach. "Particularly in gastric cancer, but occasionally in other tumour entities, GPR68-positive macrophages were present in tumour tissues." (PMID 31652823, 2019).
HCMV infection (1 paper, 2017). "In addition to these, HCMV infection of cord DCs resulted in a suppression of several other GPCRs [including GPR68, GPR183 (EBI2), and GPR146] that, together with C5AR1, CXCR4, and RGS18, have been shown to be highly enriched in unstimulated macrophages and dendritic cells." (PMID 28993767, 2017).
Interstitial cardiac fibrosis (1 paper, 2025). A type of myocardial fibrosis characterized by excessive diffuse collagen accumulation concentrated in interstitial spaces. "Heart-to-tibia length, total cardiac fibrosis and perivascular fibrosis remained similar independent of diet or genotype; however, interstitial cardiac fibrosis was lower in GPR68 KO mice and was reduced by a high-fibre diet." (PMID 40560060, 2025). "Notably, GPR68 deletion did not increase Ang II-induced interstitial cardiac fibrosis in male mice." (PMID 40560060, 2025).
invasive ductal carcinoma (1 paper, 2022). "Upon validation of this data with qPCR, the triple-negative adenocarcinoma MDA-MB-231 showed the highest expression of GPR68 at the mRNA level, followed by the luminal A MCF-7 cell line, followed by Her2+ SkBr3 and lastly the triple-negative invasive ductal carcinoma BT-549." (PMID 35311103, 2022).
myeloid malignancies (1 paper, 2021). "Delineation of the signaling pathways downstream of GPR68 and RCAN1 uncovers novel therapeutic targets that enhance the sensitivity to lenalidomide, especially in R/R and aggressive myeloid malignancies irrespective of del(5q)." (PMID 34680233, 2021).
neurofibroma (1 paper, 2024). An intraneural or extraneural neoplasm arising from nerve tissues and neural sheaths. "Altogether, these results support the possibility of using different agents to activate GPR68 in combination with selumetinib to exert a detrimental effect on neurofibromas." (PMID 38175707, 2024).
oral cancer (1 paper, 2025). "Notably, in oral cancer studies, GPR68 deletion can aggravate chemically induced oral dysplasia, indicating that GPR68 activation may have a protective effect in oral cancer." (PMID 41190345, 2025).
peritoneal carcinoma (1 paper, 2023). A peritoneum cancer that is located in the inside of the abdomen. "Therefore, one could conclude that GPR68 does not play the same role in the growth of peritoneal carcinoma tumor nodes as in the primary tumor." (PMID 36902589, 2023).
prostate) (1 paper, 2019). "In contrast, in the TRAMP (transgenic adenocarcinoma of the mouse prostate) cancer model, GPR68 deficiency led to reduced tumour formation compared to wild-type expression of GPR68." (PMID 31652823, 2019).
skin tumors (1 paper, 2020). "In this study, we have examined the expression profiles of the pH-GPCRs GPR4 (GPR19), TDAG8 (GPR65), OGR1 (GPR68) and G2A (GPR132) on different types of common skin tumors, SCC, MM, NCN and BCC." (PMID 32948783, 2020).
uremia (1 paper, 2021). A clinical syndrome associated with the retention of renal waste products or uremic toxins in the blood. "We observed monocytic expression of GPR68 and cardiac fibrosis in mice within 8 weeks after the 5/6Nx operation due to the decrease in their survival rate associated with uremia, decline in the glomerular filtration rate, and high urea nitrogen levels." (PMID 33986294, 2021).
tumor (45 papers, 2009 to 2026). "In cancer-associated fibroblasts, GPR68 senses the acidic tumor microenvironment and enhances IL-6 expression via a cAMP-PKA-CREB pathway, thereby promoting tumor cell proliferation." (PMID 41595528, 2026). "For example, GPR68-deficient mice have significantly higher infiltrating lymphocytes in tumour tissue." (PMID 40560060, 2025). "GPR68 has pleiotropic effects on tumorigenesis and has multifaceted roles in tumor cells, immune cells, and cancer-associated fibroblasts (CAFs)." (PMID 39336742, 2024). "Mounting evidence implicates acid-sensing GPCRs in the progression of various cancers, with prior literature suggesting that anti-tumor effects of GPR68 inhibition involves modulation of cancer-associated fibroblasts." (PMID 38291540, 2024). "Previous studies have shown that GPR68 promotes connections between tumor cells and cancer‐associated fibroblasts, which in turn can contribute to carcinogenesis." (PMID 37864422, 2023). "GPR68 is sensor for acid and mechanical stimulations, which are two important factors in the microenvironment associated with tumor growth and metastasis." (PMID 37350933, 2023). "A previous study demonstrated that macrophages with GPR68 deficiency are more potent than wild-type macrophages at suppressing tumor growth, correlating with iNOS expression." (PMID 36611126, 2023). "GPR68, a kind of pH-sensing protein, was associated with tumor cell biology, such as tumor aggressiveness by triggering the intracellular signaling cascade to promote the development of microenvironment of extracellular acidification." (PMID 29850522, 2018). "Furthermore, studies have demonstrated that GPR68 deficiency enhances radiotherapy sensitivity and promotes ferroptosis across multiple tumor types." (PMID 40528120, 2025). "GPR68 is closely associated with tumor proliferation, invasion, and metastasis." (PMID 41190345, 2025). "Additionally, after inoculation of melanoma B16-F10 cells into GPR68-deficient mice, decreased tumour size compared to wild-type animals was observed." (PMID 31652823, 2019). "Finally, the pro-opiomelanocortin-derived peptide 148 (Corticotropin17-40) and GPR68 both have strong associations with genetic and neoplastic disease." (PMID 31675498, 2019). "The available evidence from bone, intervertebral disk, intestinal, airway, and tumor models supports a working model in which GPR68 functions as a proton-sensing hub capable of influencing OA-relevant gene programs when joint pHe falls into the acidic range." (PMID 41595528, 2026). "The study further revealed elevated GPR68 expression in pancreatic ductal adenocarcinoma (PDAC), potentially elucidating the mechanism underlying lorazepam-mediated tumor-protective effects." (PMID 40528120, 2025). "In oncology, several studies have shown a close relationship between GPR68 and tumor prognosis, drug resistance, and tumor metastasis." (PMID 41190345, 2025). "Emerging evidence has revealed that GPR68 is also overexpressed in T cells and can modulate tumor immune evasion." (PMID 40061137, 2025). "In GBM, knocking down GPR68 or using the GPR68 inhibitor ogremorphin significantly reduces tumor cell survival." (PMID 41190345, 2025). "GPR68 is not only a promising tumor biomarker but also a potential therapeutic target for chronic inflammatory and neoplastic diseases, and it can be used to evaluate the prognosis of patients and select appropriate therapeutic strategies." (PMID 41190345, 2025). "For example, in pancreatic and colorectal cancers, CAFs express GPR68, which increases the secretion of proinflammatory cytokines, facilitates inflammatory signaling, and affects the tumor immune response." (PMID 41190345, 2025). "GPR68 regulates signal transduction pathways that are essential for several processes in tumor biology, such as cell proliferation, inhibition of apoptosis, invasion, angiogenesis, and metastasis." (PMID 40061137, 2025).
tumor (continued). "In clinical studies, the inhibition of GPR68 expression and blocking of GPR68 signaling slowed the growth and spread of tumor cells." (PMID 41190345, 2025). "In PC tissues, the GPR68 expression levels correlate with tumor aggressiveness and prognosis, making it a potential biomarker and therapeutic target." (PMID 41190345, 2025). "By assessing GPR68 expression in a patient’s tumor, it is possible to more accurately predict patient survival and tumor development." (PMID 41190345, 2025). "Together, these studies suggest that GPR68 regulates immune cell function, modulates the tumor immune microenvironment, and functions as a potential immune checkpoint to control tumor development." (PMID 39336742, 2024). "It was determined there was a significant reduction in tumor volume in the GPR68-KO mice in comparison to the WT mice." (PMID 39336742, 2024). "Overall, our data suggests that GPR68 expression protects against the severity of chemical-induced oral dysplasia in a tumor cell-extrinsic manner." (PMID 36611126, 2023). "During the first 14 days, tumor growth was reduced in the GPR68 KO group and tumors were more fibrotic, less vascular, and had more pronounced borders." (PMID 36902589, 2023). "Overall, we demonstrate that endogenous GPR68 expression limits the severity of chemical-induced OED in a tumor-extrinsic manner, suggesting a protective role in carcinogenesis." (PMID 36611126, 2023). "To see if sex hormones directly regulate GPR68 activity in the tumor cells, we examined the effect of β-Estradiol and testosterone on GPR68-mediated calcium transients in B16-F10 cells." (PMID 37350933, 2023). "The fact that GPR68 is able to increase IL-6 expression is important since IL-6 plays a fundamental role in tumor progression." (PMID 36902589, 2023). "Consistent with previous studies, we found that the tumor in WT male mice grew to ~800 mm3 and ~0.7 g on average at day 11-14, but tumor in Gpr68-/- male mice is significantly smaller." (PMID 37350933, 2023). "Our results show the gender-dependent modulatory effect of GPR68 on tumor-infiltrating immune cells and their tumor-killing capacity." (PMID 37350933, 2023). "Given the link to Treg elevation in clinical cases, future studies are necessary to determine how the tumor microenvironment, including GPR68 expression, regulates their accumulation and function." (PMID 36611126, 2023). "In the repressed tumor tissue in Gpr68-/- male mice, higher percentage of CD8+ T and NK cells were observed with a higher level of IFNγ expression." (PMID 37350933, 2023). "Meanwhile, other immune cells, including CD4+ T cells, monocytes and neutrophiles all had similar presence in tumor tissues among WT and Gpr68-/- mice, in both males and female." (PMID 37350933, 2023). "Emerging evidence show that GPR68, a G protein-coupled receptor that is sensitive to acid and mechanical stimulations for cellular microenvironment, plays an important role in tumor biology." (PMID 37350933, 2023). "Transplanting cancerous cells into GPR68−/− mice reduced tumor development through augmented function of cytotoxic CD8 T cells and macrophages." (PMID 36611126, 2023). "Our in-silico data revealed GPR68 expression to be highly upregulated in BC across the different tumor types." (PMID 35311103, 2022). "Such an expression pattern was further confirmed using the semi-quantification method via IHC Toolbox by Image J, where a higher expression of GPR68 was observed in BC tissues compared to non-tumor breast samples." (PMID 35311103, 2022). "More detailed analysis on the expression of GPR68 in particular tumor cell types, showed a significant expression in cancer epithelial cells and fibroblasts of pancreatic ductal adenocarcinomas and in hematopoietic and mesenchymal cells of colorectal tumors." (PMID 33113952, 2020). "As with normal tissue, a set of GPR68-positive tumour samples was additionally incubated with 16H23L16 pre-adsorbed with its immunising peptide." (PMID 31652823, 2019).